MUC1 (mucin 1, cell surface associated)
Diseases named in the same sentence as MUC1 in open-access papers (continued):
Sharing a sentence is not in itself a finding about the gene and the disease.
squamous cell carcinoma (24 papers, 2006 to 2025). A carcinoma arising from squamous epithelial cells. "Except for studies about altered expression of MUC1 in squamous cell carcinoma and oral potentially malignant disorders, studies on the association of oral epithelial MUC1 with oral diseases or conditions are sparce." (PMID 36458033, 2022). "In addition, cytoplasmic accumulation of β-catenin in adenocarcinoma and MUC1 expression in squamous cell cancer was associated with shorter survival." (PMID 27462437, 2016). "Conversely, the expression of ERBB3, MSLN, and MUC-1 was markedly elevated in adenocarcinoma relative to squamous cell carcinoma." (PMID 40046734, 2025). "ERBB3, MSLN, and MUC-1 expression was markedly elevated in adenocarcinoma relative to squamous cell carcinoma." (PMID 40046734, 2025). "Adenocarcinoma organoids had only MUC1-positive cells with few ciliated cells, and squamous cell carcinoma organoids were consisted of p63-positive cells with few ciliated cells." (PMID 31488816, 2019). "MUC1 expression was also increased among areas of squamous cell carcinoma versus dysplastic areas (mean difference = 0.44, 95% CI, −0.006-infinity; P = 0.052)." (PMID 30479696, 2018). "An interesting finding that we observed in the present study was the correlation between squamous carcinoma and dysplasia MUC1 expression and increased overall survival." (PMID 30479696, 2018). "MUC1 has been shown to be overexpressed or aberrantly expressed in both adenocarcinoma and squamous carcinoma NSCLC, as well as in premalignant lesions, including squamous metaplasia and squamous dysplasia." (PMID 30479696, 2018). "One patient in the present study with confirmed squamous cell carcinoma and strong (3+) MUC1 expression exhibited a prolonged, durable response to treatment; this treatment currently involves therapy with a PD-1 inhibitor." (PMID 30479696, 2018). "MUC1 expression levels among areas of squamous cell carcinoma were also increased versus dysplastic areas (mean difference = 0.44, 95% CI, −0.006 to infinity; P = 0.052)." (PMID 30479696, 2018). "Moderate staining for MUC1 was observed in keratin pearls which are distinctive feature of grade 1 squamous cell carcinoma (depicted by arrow)." (PMID 24671186, 2014). "MUC1 overexpression appears to be increased with the progression of premalignant lung lesions to invasive carcinoma in patients with NSCLC (significantly for squamous cell carcinoma and with a trend toward significance for adenocarcinoma)." (PMID 30479696, 2018). "In adenocarcinoma, particular interest has been focused on MUC1 mucin; in previous publications we have extensively detected MUC1 and associated epitopes in HNSCC and also we have isolated this mucin from larynx primary squamous cell carcinoma." (PMID 17064405, 2006). "In fact, multiple bladder tumor cell types, including transitional cell carcinomas, adenocarcinomas, and squamous cell carcinoma, exhibited upregulation in membrane complement inhibitors (CD46: 77%, CD55: 55%, CD59: 59%) after the cell samples were incubated with anti-MUC1 (mucin-1) antibodies." (PMID 34514097, 2021). "The present study demonstrated that patients with NSCLC, including both adenocarcinoma and squamous cell carcinoma, had a significant decrease in plasma IgG antibodies against the combination of three peptide antigens derived from CD25, MUC1, and VEGFR1, respectively." (PMID 32392378, 2020). "In addition, both MUC1 and MUC5AC have higher expression in adenocarcinomas compared with squamous cell carcinomas." (PMID 32807223, 2020). "MUC1 was significantly increased in adenocarcinoma (ADC) but not in squamous cell carcinoma (SCC) through glycoproteomics and proteomic analysis of NSCLC tissue samples." (PMID 30646616, 2019). "A humoral response to MUC1 is present in patients with adenocarcinomas of the genital tract, but not in patients with squamous cell carcinoma (SCC) of the cervix." (PMID 24212946, 2011).
asthma (22 papers, 2012 to 2025). "Although MUC1 was found to be associated with neutrophil inflammation in asthma, the association of MUC1 with eosinophilic airway inflammation is unclear." (PMID 39791734, 2024). "This study explored the inhibitory effect of MUC1 on NLRP3 inflammasome-mediated pyroptosis in patients with asthma and revealed that one of the underlying mechanisms is the downregulation of TLR4/MyD88/NF-κB pathway activation." (PMID 37880668, 2023). "Previous studies have demonstrated that MUC1 deficiency mediates corticosteroid insensitivity in patients with asthma." (PMID 37880668, 2023). "MUC1, which was also associated with better response to omalizumab, is important in allergen response as well as corticosteroid response in asthma patients." (PMID 38057814, 2023). "This study aimed to explore the influence of MUC1 on neutrophil airway inflammation in patients with asthma and verify the underlying mechanism associated with the TLR4/MyD88/NF-κB pathway and NLRP3 inflammasome-mediated pyroptosis." (PMID 37880668, 2023). "In the female EWAS, genes well known to be linked with asthma include MUC1, RASGRF1 and IL9138." (PMID 40410506, 2025). "Based on the theory that correct MUC1-CT/GRα complex formation and nuclear translocation are important to enhance corticosteroid anti-inflammatory inducible genes, they proposed that MUC1 deficiency impairs corticosteroid insensitivity in patients with asthma." (PMID 37880668, 2023). "In contrast, this study regarded NLRP3 inflammasome activation as an initiation of pyroptosis and revealed the downregulation effect of MUC1 on pyroptosis in asthma." (PMID 37880668, 2023). "Consistent with the in vitro results, these in vivo results more intuitively clarified the role of MUC1 in reducing neutrophilic airway inflammation in asthma." (PMID 37880668, 2023). "MUC1 knock-out mice are resistant to the anti-inflammatory effects of corticosteroids, and in a study of patients with asthma sensitized to pigeon, MUC1 was upregulated when these patients were exposed to the pigeon allergen." (PMID 38057814, 2023). "However, the reason for MUC1 expression downregulation in the course of asthma remains unknown, and more research may be needed in the future to prevent MUC1 deficiency or increase MUC1 expression in asthma." (PMID 37880668, 2023). "In summary, this study revealed that MUC1 was downregulated in induced sputum of patients with asthma and played an important role in neutrophilic airway inflammation." (PMID 37880668, 2023). "The greatest significance of this study is to reveal the potential protective role of MUC1 in neutrophil airway inflammation in patients with asthma." (PMID 37880668, 2023). "The mRNA expression of MUC1 was downregulated in the induced sputum of patients with asthma and correlated with asthmatic neutrophilic airway inflammation." (PMID 37880668, 2023). "We have demonstrated that NSAID intolerance correlates with worse QoL measured with the SNOT-22 tool when also considering the influence of MUC1, asthma and eosinophils." (PMID 36835929, 2023). "The present study revealed that MUC1 expression in induced sputum of patients with asthma was downregulated and was related to asthma severity." (PMID 37880668, 2023). "In recent years, several studies have revealed that MUC1 has a potent anti-inflammatory function in the respiratory system, and its role in asthma has also received some attention." (PMID 37880668, 2023). "Although MUC1 has been suggested to have a significant role in apoptosis, little is known about the link between MUC1 and necroptosis in asthma." (PMID 30666647, 2019). "qPCR confirmed that S100P, S100A16, MAL and MUC1 were significantly increased in the asthma group post-meal." (PMID 26751474, 2016). "Confirming the microarray analysis, we determined that S100P, S100A16, MAL and MUC1 were significantly increased in the asthma group at 4 h post-meal compared with baseline." (PMID 26751474, 2016).
asthma (continued). "Interestingly, in patients with severe asthma or CRSwNP, MUC1-CT downregulation reduces corticosteroid responses because of the impaired glucocorticoid receptor (GR) translocation into the nucleus." (PMID 39791734, 2024). "First, we collected induced sputum samples from 64 patients to detect whether MUC1 expression is altered in the airways of patients with asthma." (PMID 37880668, 2023). "However, a previous study reported changes in the expression levels of MUC1 in bronchial epithelial cells and blood neutrophils of patients with asthma, and our study supplemented the changes in induced sputum cells." (PMID 37880668, 2023). "The mRNA expressions of TLR4, MyD88, nucleotide-binding oligomerization domain-like pyrin domain-containing protein 3 (NLRP3), caspase-1, interleukin (IL)-18, and IL-1β in induced sputum cells of patients with asthma were upregulated and related to the mRNA expression of MUC1." (PMID 37880668, 2023). "In fact, corticosteroid refractoriness, an important issue in the management of BA, could be identified by the downregulation of mucin-1 (MUC-1) in circulating neutrophils, a characteristic of patients with uncontrolled severe asthma." (PMID 36835081, 2023). "This study suggested a possible mechanism of neutrophilic airway inflammation in patients with asthma and emphasized the anti-inflammatory function of MUC1 in neutrophilic asthma, thereby indicating that MUC1 is of a potential value to develop new asthma treatment strategies." (PMID 37880668, 2023). "This study shows the role of MUC1 in attenuating neutrophil-induced airway inflammation, further emphasizing the importance of MUC1 in the pathogenesis of asthma, which may have a potential value for developing new treatment strategies for refractory asthma." (PMID 37880668, 2023). "Mucin 1 (MUC1), which contains a cytoplasmic tail (MUC1-CT), has been found to mediate glucocorticoid sensitivity in asthma; however, its role in modulating neutrophilic airway inflammation in asthma remains unknown." (PMID 37880668, 2023). "MUC1 may also influence resistance to corticosteroid treatments, which is related to corticosteroid resistance in patients with asthma." (PMID 35469047, 2022). "Collectively, these data suggest that Nec‐1 can antagonize TNF‐α‐induced necroptosis in 16HBE cells with MUC1 downregulation and thus, furtherly support that MUC1 as a novel protective molecule in cell necroptosis on asthma through mediating the p‐RIPK1‐s166 expression." (PMID 30666647, 2019). "Interestingly, previous studies had shown the anti-inflammatory function of MUC1 in asthma, by reducing the NLRP3 inflammasome-mediated pyroptosis through the inhibition of the TLR4/MyD88/NF-κB pathway, thereby suppressing neutrophilic airway inflammation in patients with asthma." (PMID 41295249, 2025). "However, whether MUC1 regulates NLRP3 inflammasome-mediated pyroptosis through the TLR4/MyD88/NF-κB pathway in asthma remains unknown." (PMID 37880668, 2023). "However, neutrophilic airway inflammation regulation by MUC1 is unclear in asthma." (PMID 37880668, 2023). "However, little is known about the link between MUC1 and necroptosis in asthma." (PMID 30666647, 2019). "Moreover, we discovered that MUC1 expression was significantly negatively correlated with the proportion of neutrophils in induced sputum of patients with asthma, indicating that MUC1 may have an inhibitory effect on neutrophil airway inflammation in asthma." (PMID 37880668, 2023). "The mRNA expression of MUC1 in induced sputum cells was negatively correlated with FEV1 (% predicted) and FEV1/FVC for patients with asthma (n = 52) and positively correlated with the proportion of neutrophils in induced sputum." (PMID 37880668, 2023).
asthma (continued). "This study highlights the complex interaction between the circadian clock and the pathophysiological features of asthma, particularly highlighting the role of BMAL1 in the regulation of MUC1 expression, which is a key component in the airway’s mucosal defense mechanism." (PMID 41473388, 2025). "MUC1-CT reduces NLRP3 inflammasome-mediated pyroptosis by inhibiting the activation of the TLR4/MyD88/NF-κB pathway, thereby attenuating neutrophil airway inflammation in patients with asthma." (PMID 37880668, 2023). "Mechanistic studies revealed that MUC1 reduced NLRP3 inflammasome-mediated pyroptosis by inhibiting TLR4/MyD88/NF-κB pathway activation, thereby suppressing neutrophilic airway inflammation in patients with asthma." (PMID 37880668, 2023). "In addition, the protein expression levels of NLRP3, caspase-1, cleaved caspase-1, GSDMD, GSDMD-N, IL-18, and IL-1β were increased, indicating that MUC1, TLR4/MyD88/NF-κB pathway, and NLRP3-induced pyroptosis are involved in the pathogenesis of asthma." (PMID 37880668, 2023). "Furthermore, this study adds to the evidence that MUC1 regulates the TLR4/MyD88/NF-κB pathway and NLRP3 inflammasome-mediated pyroptosis in patients with asthma." (PMID 37880668, 2023). "In our study, we examined the expression levels of critical members of the mucin family, specifically the secreted mucins MUC5AC and MUC5B, in addition to the membrane-bound mucins (MUC1, MUC4, and MUC2) in lung tissue obtained from the TIMPKO murine asthma model." (PMID 34221020, 2021). "The findings suggest that the circadian regulation of MUC1 by BMAL1 may hold significant implications for understanding the temporal dynamics of asthma symptoms and potentially inform therapeutic strategies targeting the circadian clock to mitigate asthma pathologies." (PMID 41473388, 2025).
glioblastoma (19 papers, 2007 to 2025). The most malignant astrocytic tumor (WHO grade IV). "Knockdown of MUC1 in glioblastoma cell lines, U373 and T98G, decreased proliferation and induced cell cycle arrest." (PMID 34069193, 2021). "Finally, sequencing of paired patient-derived normal and glioblastoma tissue revealed elevated expression of Mucin 1 (MUC1) in tumors." (PMID 34069193, 2021). "Finally, several other antigens on glioblastoma are targeted in other trials, e.g., ephrin type-A receptor 2 (EphA2) (NCT02575261), GD2 (NCT03252171), and mucin 1 (MUC1) (NCT02839954, NCT02617134)." (PMID 31779130, 2019). "However, the role of MUC1 in glioblastoma (GBM) has not yet been fully explored." (PMID 33106534, 2020).
metastatic disease (19 papers, 2008 to 2025). "Previous studies have shown that MUC1 is diffusely overexpressed in cRCC and MUC1 overexpression has been found to be associated with metastatic disease and a worse prognosis." (PMID 24504508, 2014). "In patients with locally advanced or metastatic disease, overexpression and altered glycosylation of MUC1 are frequently observed." (PMID 40001578, 2025). "In further support of MUC1-C as a novel target for pNET treatment, we found that MUC1 gene expression is upregulated in primary pNET tumors that progress with metastatic disease." (PMID 39062082, 2024). "We found that MUC1 expression is upregulated in primary pNETs that progress with metastatic disease." (PMID 39062082, 2024). "We demonstrate that the MUC1 gene is upregulated in primary pNETs that progress with metastatic disease." (PMID 39062082, 2024). "An analysis of the GSE178398 dataset derived from 22 primary pNET lesions demonstrated that MUC1 mRNA levels are significantly higher in those that progress with metastatic disease." (PMID 39062082, 2024). "Further, BC patients with metastatic disease have a higher level of circulating MUC1 than patients with primary BC." (PMID 36980526, 2023). "The CA15-3 assay detects the soluble forms of MUC1 (the peptide backbone), and it is used for therapy monitoring in patients with metastatic disease." (PMID 37455827, 2023). "CTCs are released from a primary or metastatic tumor and shed into the peripheral blood, where they can be isolated by size selection or by targeting surface proteins such as EpCAM, MUC1, or HER2." (PMID 36430255, 2022). "The metastatic tumors had significantly higher levels of MUC1 expression compared with non-metastatic tumors." (PMID 31470870, 2019). "Significantly more patients with high IL-8, CEA, platelet derived growth factor alpha (PFGFRalpha), and mucin 1 (MUC-1) levels had stage IV metastatic disease.." (PMID 26808546, 2016). "IL-8 and CEA were also more likely to be elevated in patients with metastatic disease, as were, MUC-1 and PDGFRalpha." (PMID 26808546, 2016). "Our results concur with several studies, signifying that CA 15.3, which detects soluble forms of MUC1 oncoprotein, is valuable for monitoring therapy in patients with metastatic disease." (PMID 23653670, 2013). "We show that MUC1 expression is upregulated in primary pNETs that progress with metastatic disease." (PMID 39062082, 2024). "Blood was obtained at the time of first diagnosis of metastatic disease or disease progression and analyzed for CTCs using the AdnaTest BreastCancer (QIAGEN Hannover GmbH, Germany) for the expression of EpCAM, MUC-1, HER2, ER and PR." (PMID 27456970, 2016). "In a recent analysis, multiple mucins, including MUC1, MUC2, MUC5AC, and MUC6, were found to differentiate primary BC from metastatic BC, where MUC1 correlated with the low or early grade, MUC5AC with metastatic disease, and MUC6 emerged as an indicator of poor prognosis." (PMID 36980526, 2023).